ATP6V1G1 (ATPase H+ transporting V1 subunit G1)
Description:
Subunit of the V1 complex of vacuolar(H+)-ATPase (V-ATPase), a multisubunit enzyme composed of a peripheral complex (V1) that hydrolyzes ATP and a membrane integral complex (V0) that translocates protons. V-ATPase is responsible for acidifying and maintaining the pH of intracellular compartments and in some cell types, is targeted to the plasma membrane, where it promotes acidification of the extracellular environment. The V-ATPase complex also acts as an activator for mTORC1 on lysosomal membrane by promoting the guanine nucleotide exchange factor (GEF) of the Ragulator complex, thereby enabling mTORC1 recruitment. In aerobic conditions, involved in intracellular iron homeostasis, thus triggering the activity of Fe(2+) prolyl hydroxylase (PHD) enzymes, and leading to HIF1A hydroxylation and subsequent proteasomal degradation.
Synonyms: ATP6G; ATP6G1; ATP6J; ATP6GL; Vma10; DKFZp547P234
Tractability: Small molecule: a structure with a bound ligand is known. Antibody: UniProt places it where antibodies can reach, with high confidence; its Gene Ontology location is reachable by antibodies, with high confidence. PROTAC: ubiquitination databases record sites on it; its protein half-life has been measured.
Gene: Protein-coding gene on chromosome 9 (114,587,706 to 114,598,915, forward strand). Ensembl gene ENSG00000136888.
Subcellular location: Apical cell membrane
Subcellular location (Human Protein Atlas): Nucleoli; Nucleoplasm
Pathways (Reactome):
Transport of small molecules: Ion channel transport; Transferrin endocytosis and recycling
Cellular responses to stimuli: Amino acids regulate mTORC1
Developmental Biology: Regulation of MITF-M-dependent genes involved in lysosome biogenesis and autophagy
Immune System: ROS and RNS production in phagocytes
Signal Transduction: Insulin receptor recycling
Gene Ontology:
Molecular function: ATPase binding; protein binding; proton transmembrane transporter activity; proton-transporting ATPase activity, rotational mechanism
Biological process: cellular response to increased oxygen levels; intracellular iron ion homeostasis; regulation of macroautophagy; synaptic vesicle lumen acidification; proton transmembrane transport
Cellular component: apical plasma membrane; extracellular exosome; lysosomal membrane; plasma membrane; vacuolar proton-transporting V-type ATPase, V1 domain; cytosol; synaptic vesicle membrane; extrinsic component of synaptic vesicle membrane; proton-transporting V-type ATPase complex; proton-transporting V-type ATPase, V1 domain; vacuolar proton-transporting V-type ATPase complex
Genetic constraint (gnomAD): Loss-of-function variants: 14 observed, 9.5 expected, observed/expected ratio (o/e) 1.47, 90% interval 0.95 to 1.92. That is too few expected variants to judge how well the gene tolerates losing a copy. Missense variants: 137 observed, 121.26 expected, observed/expected ratio (o/e) 1.13, 90% interval 0.98 to 1.3. Synonymous variants: 65 observed, 42.12 expected, observed/expected ratio (o/e) 1.54, 90% interval 1.26 to 1.87.
Homologues: Orthologues: chimpanzee ATP6V1G1 (100% identical), macaque ATP6V1G1 (99% identical), pig ATP6V1G1 (98% identical), rat Atp6v1g1 (97% identical), mouse Atp6v1g1 (95% identical), guinea pig ATP6V1G1 (91% identical), tropical clawed frog atp6v1g1 (81% identical), zebrafish atp6v1g1 (77% identical). Paralogues in human: ATP6V1G2 (64% identical), ATP6V1G3 (53% identical).
Diseases named in the same sentence as ATP6V1G1 in open-access papers:
ATP6V1G1 is named in the same sentence as 23 diseases in open-access papers, as found by Europe PMC text mining. Sharing a sentence is not in itself a finding about the gene and the disease. The quoted sentences say what the papers report.
glioblastoma (4 papers, 2015 to 2024). The most malignant astrocytic tumor (WHO grade IV). "Previous studies have shown that high levels of ATP6V1G1 are associated with short overall survival in glioblastoma (GBM) and ATP6V1G1 interacts with other factors to reprogram the surrounding non-tumor microenvironment to a pro-tumor state." (PMID 39621600, 2024). "In glioblastoma, high expression of ATP6V1G1 is associated with poor prognosis." (PMID 33194650, 2020).
glioma (3 papers, 2015 to 2025). A benign or malignant brain and spinal cord tumor that arises from glial cells (astrocytes, oligodendrocytes, ependymal cells). "Among the V-ATPase subunits analyzed, ATP6V1G1 (V-ATPase G1) was the most expressed in human gliomas, whereas expression of the V-ATPase G1 paralog ATP6V1G3 was absent in all cases and therefore was excluded from further analysis." (PMID 26020805, 2015). "The high expression of ATP6V1G1 promotes the proliferation and migration of glioma stem cells." (PMID 39621600, 2024). "Concluding, our results suggest that high levels of ATP6V1G1 are a characteristic of GBM stem cells and could influence the onset of chemoresistance typical of high grades gliomas." (PMID 26020805, 2015). "Interestingly, ATP6V1G1 expression was also high in commercially available GBM cells (LN229 and T98G) compared to a less aggressive line (SW1088), and in high-grade human glioma tissues compared to grade II tumors." (PMID 26020805, 2015). "In contrast, in adherent glioma cultures or LN229 cells, cell death, caspase 3/7 activity or cell cycle transition was not affected by ATP6V1G1 levels." (PMID 26020805, 2015). "This analysis showed that ATP6V1G1 and ATP6V0A2 are frequently over-expressed in gliomas compared to non-neoplastic brain tissues without concomitant up-regulation of other subunits." (PMID 26020805, 2015).
amyotrophic lateral sclerosis (1 paper, 2024). Amyotrophic lateral sclerosis (ALS) is a neurodegenerative disease characterized by progressive muscular paralysis reflecting degeneration of motor neurons in the primary motor cortex, corticospinal tracts, brainstem and spinal cord. "ATP6V1G1 overexpression due to UBQLN2 mutations has been found to cause amyotrophic lateral sclerosis (ALS), frontotemporal dementia (FTD), and other neurodegeneration." (PMID 39621600, 2024).
hepatocellular carcinoma (1 paper, 2024). A malignant tumor that arises from hepatocytes. "Previous studies have indicated that ATP6V1G1 plays important roles in hepatocellular carcinoma (HCC) and is associated with HCC progression." (PMID 39621600, 2024). "Another shortcoming is that while we have identified the proteins that become phosphorylated in response to ATP6V1G1 overexpression in hepatocellular carcinoma (HCC) cell lines, we have not delved into the direct effects of these phosphorylation alterations on the overall protein expression profile." (PMID 39621600, 2024).
liver cancer (1 paper, 2024). An epithelial or non-epithelial malignant neoplasm that arises from the liver. "Taken together, this study highlighted the potential impact of ATP6V1G1 on tumor progression, which may be beneficial to liver cancer related basic research." (PMID 39621600, 2024).
multiple sclerosis (1 paper, 2024). A progressive autoimmune disorder affecting the central nervous system resulting in demyelination. "This study identified IREB2, LAMP2, ISCU, ATP6V1G1, ATP13A2, and SKP1 as genes associated with multiple sclerosis (MS) and iron metabolism, establishing their multi-gene diagnostic value for MS with an AUC of 0.83." (PMID 38590521, 2024).
nonalcoholic fatty liver disease (1 paper, 2024). "Meanwhile, ATP6V1G1 regulates liver lipid metabolism by maintaining the normal acidification function of lysosomes, suggesting that ATP6V1G1 may play an important role in the development of nonalcoholic fatty liver disease." (PMID 39621600, 2024).
tumor (2 papers, 2022 to 2024). "In the previous study, ATP6V1G1 was highly expressed in HCC and closely related to tumor cell proliferation, apoptosis, and migration." (PMID 39621600, 2024). "In contrast, this study revealed that ATP6V1G1 at 9q and PSMA6 at 14q might be potential tRCC tumor suppressors." (PMID 36470859, 2022).
ATP6V1G1 also shares sentences with these, for which no sentence is quoted: cancer (3 papers); renal cell carcinoma (2); asthma (1); breast carcinoma (1); COVID-19 (1); esophageal squamous cell carcinoma (1); frontotemporal dementia (1); gastric cancer (1); hematological disease (1); infection (1); kidney disease (1); oral squamous cell carcinoma (1); osteoporosis (1); ovarian carcinoma (1); rheumatoid arthritis (1).